G3BP1 (G3BP stress granule assembly factor 1)
Diseases named in the same sentence as G3BP1 in open-access papers (continued):
Sharing a sentence is not in itself a finding about the gene and the disease.
prostate carcinoma (10 papers, 2020 to 2025). A carcinoma that arises from epithelial cells of the prostate gland. "In recent years, G3BP1 has been reported to promote the development of prostate cancer by inhibiting the degradation of AR through inhibiting SPOP." (PMID 37904149, 2023). "We observed that the G3BP1-SPOP axis regulates invasion potential of 22RV1 human prostate cancer cells." (PMID 35252555, 2022). "To evaluate the expression and contributions of G3BP1 in prostate cancer tissue, we analyzed TCGA RNA sequencing (RNA-seq) data from 498 patient samples and observed that G3BP1 expression is high in higher prostate cancer Grade Group36." (PMID 34795264, 2021). "Taken together, our findings elucidate a critical KMT2D/G3BP1/SPOP/AR regulatory axis in prostate cancer progression and propose that targeted inhibition of histone methylation in combination with anti-androgen therapy represents a promising strategy for the management of advanced prostate cancer." (PMID 41247636, 2025). "G3BP1 may serve as a new prognostic biomarker in prostate cancer and provide an opportunity for precision therapy of such G3BP1high patients." (PMID 35252555, 2022). "In addition, in SPOP-null C4-2B prostate cancer cells, the turnover rate (half-life) of G3BP1 remains unchanged compared with the parental SPOP-wt C4-2B cells." (PMID 34795264, 2021). "Together, these results strongly point to a key role for G3BP1 as a cytoprotective factor in prostate cancer cells, likely through its effects on partitioning of transcripts between different mRNA compartments for activation or suppression of their translation." (PMID 32406909, 2020). "G3BP1 expression gradually increased in tissue samples of benign to primary PCa tumors and was likely most abundant in CRPC (p < 0.001, χ2 test) suggesting that G3BP1 overexpression is associated with more aggressive disease across the clinical spectrum of prostate cancer." (PMID 34795264, 2021). "Inspired by the findings that the AR signaling pathway is one of the most deregulated pathways by the G3BP1-SPOP ubiquitin signaling axis, we set to investigate its potential role in prostate cancer pathogenesis." (PMID 35252555, 2022). "Here, we have identified G3BP1 as an interactor of SPOP and functions as a competitive inhibitor of Cul3SPOP, suggesting a distinctive mode of Cul3SPOP inactivation in prostate cancer (PCa)." (PMID 34795264, 2021). "RASSF2, which is a tumor-suppressor in the prostate cancer mouse model, might be coregulated by FXR1, FXR2, HNRNPA1, PTBP1, G3BP1, HNRNPF, and SRSF7." (PMID 32316190, 2020). "Here, we identified GTPase Activating Protein (SH3 Domain) Binding Protein 1 (G3BP1) as an interactor and upstream regulator of CUL3SPOP, and it functions as an inhibitor of CUL3SPOP ubiquitin ligase, suggesting a distinctive mode of CUL3SPOP inactivation that aggravates prostate cancer." (PMID 35252555, 2022).
COVID-19 (7 papers, 2021 to 2024). A disease caused by infection with severe acute respiratory syndrome coronavirus 2. "MKRN2, together with G3BP1/2, has been suggested to regulate olfactory signaling mRNAs25, pointing to potential mechanistic links underlying anosmia in COVID-19." (PMID 36217029, 2023). "Recent studies highlighted the potential anti-viral role of G3BP1 in the lung tissue of COVID-19 patients and SARS-CoV-2-infected mice." (PMID 36851663, 2023). "Thus, targeting the N protein function in G3BP1 SG regulation represents a new and valid strategy to fight COVID-19." (PMID 34029587, 2021). "Notably, the in situ interaction of NPSARS-CoV-2 with G3BPs was observed in the lungs of patients with COVID-19 with the S protein of SARS-CoV-2 and G3BP1 (or G3BP2) as a control." (PMID 35652658, 2022).
poliovirus infection (6 papers, 2011 to 2021). An disease or disorder caused by infection with Enterovirus C. "For example, RSV triggers stable SG formation throughout the viral life cycle, while poliovirus infection causes a transient SG formation during the early phase of infection, but disperses the resulting SGs by cleavage of G3BP1 during later stages of infection." (PMID 28421170, 2017). "For example, expression of a cleavage-resistant G3BP1 restored SG formation during poliovirus infection and significantly inhibited virus replication." (PMID 28421170, 2017). "Previously G3BP1 had been reported to be antagonized in poliovirus infection, where it is cleaved by a viral protease." (PMID 24992036, 2014).
ZIKV infection (6 papers, 2017 to 2025). "It is possible that G3BP1 was cleaved during ZIKV infection; however, the modest decrease in G3BP1 levels likely limited the detection of such a fragment by Western blot analysis." (PMID 30944179, 2019). "We also investigated the role of different stress granule proteins in ZIKV infection by using target-specific short interfering RNAs to deplete Ataxin2, G3BP1, HuR, TIA-1, TIAR, and YB1." (PMID 30944179, 2019). "Our systematic analysis of SG proteins during ZIKV infection is significant particularly as G3BP1, HuR, and other SG proteins have an intimate role in neurodevelopment and function." (PMID 30944179, 2019). "To further corroborate our results from polysome profiling results and determine whether Zika virus infection selectively inhibits stress granule formation, we quantified G3BP1-positive puncta in cells exposed to poly (I:C), 3p-shRNA, UV-inactivated or live Zika virus." (PMID 39621795, 2024). "Alternatively, G3BP1 might be degraded during ZIKV infection." (PMID 30944179, 2019). "However, changes in Ataxin-2 and G3BP1 levels might in part restrict the formation of SGs during ZIKV infection." (PMID 30944179, 2019).
amyotrophic lateral sclerosis (5 papers, 2014 to 2026). Amyotrophic lateral sclerosis (ALS) is a neurodegenerative disease characterized by progressive muscular paralysis reflecting degeneration of motor neurons in the primary motor cortex, corticospinal tracts, brainstem and spinal cord. "The dipeptide repeat protein GR20 in amyotrophic lateral sclerosis (ALS) exerts neurotoxicity in part by binding to the stress granule protein G3BP1 and disrupting liquid-liquid phase separation (LLPS)." (PMID 42111176, 2026). "Phosphorylated Tar-DNA binding protein 43 (TDP-43), for example, forms pathological axonal aggregates in amyotrophic lateral sclerosis (ALS), including G3BP1." (PMID 40806415, 2025). "In this study, we developed an Anap-based labeling platform optimized for minimally disruptive labeling of two important proteins, G3BP1 and TDP-43, involved in membraneless organelles and neurodegenerative diseases, such as amyotrophic lateral sclerosis (ALS) and frontotemporal dementia (FTD)." (PMID 41279779, 2025).
colorectal cancer (5 papers, 2021 to 2025). A primary or metastatic malignant neoplasm that affects the colon or rectum. "LINC01088 directly targets miR‐548b‐5p and miR‐548c‐5p, promoting the expression of G3BP1 and PD‐L1, thereby driving colorectal cancer progression and immune evasion." (PMID 40000422, 2025). "As such, it has been reported to promote the proliferation, migration, and invasion in colorectal cancer cells via the G3BP1 pathway." (PMID 37987362, 2023). "LINC01088 directly targets miR-548b-5p and miR-548c-5p, as well as enhances the expression of G3BP1 and PD-L1, consequently boosting the development of colorectal cancer and immune evasion." (PMID 36983670, 2023).
melanoma (5 papers, 2021 to 2025). A malignant, usually aggressive tumor composed of atypical, neoplastic melanocytes. "Ratio of phosphorylated G3BP1 (P-G3BP1) and G3BP1 protein level were elevated in melanoma cell lines." (PMID 41148289, 2025). "Immunofluorescence staining revealed G3BP1 positivity in ~ 75% of melanoma tissues, compared to ~ 30% of nevi." (PMID 41148289, 2025). "While G3BP1 was consistently expressed, SG formation was only evident under strong oxidative stress, explicit by sodium arsenite, indicating that SG assembly in melanoma is a tightly regulated response to extreme stress conditions." (PMID 41148289, 2025). "Western blot analysis showed high endogenous G3BP1 expression across all tested melanoma cell lines in whole protein lysates, while normal human epidermal melanocytes (NHEM) displayed variable levels between six different donors." (PMID 41148289, 2025). "Collectively, our results suggest that downregulation of HSP70 and subsequent dephosphorylation of G3BP1 sensitize Vemurafenib-resistant melanoma cells to treatment, particularly under additional stress induced by SA." (PMID 41148289, 2025). "We observed high steady-state levels of serine 149-phosphorylated G3BP1 (P-G3BP1) in melanoma cell lines, in contrast to lower levels in pancreatic (Panc-1), hepatic (Hep3B, HepG2), and colorectal (HT29) carcinoma cells." (PMID 41148289, 2025). "Despite elevated basal expression of G3BP1, a canonical SG nucleator, in both melanoma cells and normal human epidermal melanocytes (NHEMs), this alone was insufficient to drive SG assembly, highlighting tumor-type-specific regulation." (PMID 41148289, 2025). "Our results implicate constitutive phosphorylation of G3BP1 at S149 as a key mechanism of SG suppression in melanoma." (PMID 41148289, 2025). "Collectively, our data show that melanoma cells employ at least two SG-suppressive mechanisms: constitutive G3BP1 phosphorylation and sustained HSP70 expression to maintain proteostasis and evade apoptosis." (PMID 41148289, 2025). "The effects of G3BP1 on the malignant phenotypes of melanoma cells were explored by transfecting with G3BP1 siRNA." (PMID 35902727, 2022). "The results of the Cancer Genome Atlas (TCGA) database analyzed by the Gene Expression Profiling Interactive Analysis (GEPIA) website showed that G3BP1 was overexpressed in melanoma samples." (PMID 35902727, 2022). "Altogether, we mainly investigated the functions of KPNB1 and G3BP1 in melanoma and their regulatory relationship." (PMID 35902727, 2022). "Notably, in melanoma cells, KPNB1 overexpression significantly decreased Ras-GTPase-activating protein SH3 domain-binding protein 1 (G3BP1) protein level, which was also overexpressed in melanoma samples and enhanced malignant behaviors of melanoma cells." (PMID 35902727, 2022). "GEPIA analyzed that G3BP1 was highly expressed in melanoma samples." (PMID 35902727, 2022). "Interestingly, we found that KPNB1 only affected the protein expression of G3BP1 but not the mRNA level, and KPNB1 downregulation increased the ubiquitination of G3BP1 in melanoma cells, which is similar to previous." (PMID 35902727, 2022). "Functional analysis indicated that G3BP1 knockdown reversed the effect of KPNB1 on the malignant phenotype of cells, indicating that the regulation of KPNB1 on the development of melanoma may be achieved through G3BP1." (PMID 35902727, 2022). "Herein, we demonstrated that G3BP1 plays a tumor-promoting role in melanoma progression." (PMID 35902727, 2022). "Overall, the results demonstrated that G3BP1 promoted melanoma progression." (PMID 35902727, 2022). "In addition, the invasion and migration capacities of melanoma cells were also significantly decreased in G3BP1-silenced cells." (PMID 35902727, 2022). "In summary, this study mainly reports that KPNB1 may promote melanoma progression by stabilizing the G3BP1 protein." (PMID 35902727, 2022).
melanoma (continued). "Therefore, the results suggest that KPNB1 may promote melanoma progression by stabilizing the G3BP1 protein." (PMID 35902727, 2022). "Therefore, G3BP1 might mediate the regulation of KPNB1 on melanoma progression." (PMID 35902727, 2022). "However, the function of G3BP1 in melanoma progression remains unclear." (PMID 35902727, 2022). "Given that KPNB1 could upregulate G3BP1 expression, we next investigate the role of G3BP1 in KPNB1–mediated melanoma progression." (PMID 35902727, 2022). "Although in melanoma the presence of the retinoblastoma binding (RB) mRNA Rbfox2 in SGs was associated with progression and metastasis, the presence of TIA1, G3BP1, and TIAL1 in melanoma-derived SGs has not been reported, so new experimental approaches would be needed." (PMID 39594467, 2024). "However, in addition to G3BP1, KPNB1 can also play a role in cancer by regulating the nuclear transport of substrates, such as E2F transcription factor 1 (E2F1) and p65, which play a promoting role in melanoma." (PMID 35902727, 2022).
non-small cell lung carcinoma (5 papers, 2021 to 2025). A group of at least three distinct histological types of lung cancer, including non-small cell squamous cell carcinoma, adenocarcinoma, and large cell carcinoma. "In other words, increased formation of G3BP1 reduces ROS production and inhibits radiation-induced DNA damage and apoptosis, leading to radiotherapy resistance in non-small cell lung cancer (NSCLC) cell." (PMID 37179344, 2023). "Clinical analysis further identified heightened G3BP1 expression as a robust prognostic marker, independently indicative of adverse outcomes for patients with NPC and non-small cell lung cancer (NSCLC)." (PMID 39869565, 2025). "Similarly, in non-small cell lung cancer (NSCLC), downregulation of BIN1 inhibits ferroptosis via the G3BP1/STAT1/GSH pathway, which impairs CD8+ T cell function and promotes immune evasion." (PMID 40919170, 2025). "In addition, non-small cell lung cancer patients with clinical stages II and III had higher G3BP1 and YB1 protein expression than those with stage I. Furthermore, G3BP1 protein expression was positively correlated with YB1 and pAKT." (PMID 34604242, 2021).
ovarian carcinoma (5 papers, 2021 to 2025). A malignant neoplasm originating from the surface ovarian epithelium. "In ovarian cancer, the expression of G3BP1 is increased and loss of G3BP1 inhibits the proliferation, migration and invasion of ovarian cancer cells." (PMID 36330442, 2022). "Lower expression of G3BP1 protein was exhibited in stages I while higher expression in advanced stage ovarian cancer (stages III and IV) tissues." (PMID 34967276, 2022). "We observed similar regulation of PARP14-mediated RACK1 MARylation and stress granule assembly in additional ovarian cancer cell lines, SKOV3 and HCC5044 (note the reduced number of discrete G3BP1 puncta upon PARP14i treatment)." (PMID 39760726, 2025). "The results together suggest that GIP we generated possesses the ability to block SPOCD1-AS/G3BP1 interaction, suppress MMT process of MeT-5A cells, and restrains ovarian cancer peritoneal metastasis in vitro and in vivo." (PMID 33726799, 2021). "In this study, we generated a cell-penetrating interfering peptide GIP based on the F380/F382 residues, and confirmed its capacity to block the SPOCD1-AS/G3BP1 interaction, inhibit MMT features of mesothelial cells in vitro and suppressed ovarian cancer peritoneal metastasis in vivo." (PMID 33726799, 2021).
bladder cancer (4 papers, 2011 to 2025). "In bladder cancer, G3BP1 collaborates with SLU7 to activate the PI3K/AKT pathway, leading to reduced MHC-I expression and facilitating immune escape." (PMID 40346580, 2025). "Second, in U2OS bladder cancer cells, the interaction between G3BP1 and USP10 inactivates the deubiquitinating enzyme activity of USP10." (PMID 21455491, 2011).
esophageal cancer (4 papers, 2019 to 2024). A primary or metastatic malignant neoplasm involving the esophagus. "In esophageal cancer, increased G3BP1 expression enhances the migration and invasion ability of esophageal cancer cell by activating the Wnt/β-catenin and PI3K/AKT signaling pathways." (PMID 37179344, 2023). "It has been shown that knockdown of G3BP1 downregulated the expression level of p‐PI3K (Tyr458) and p‐AKT (Ser473) in esophageal cancer cells, which supports our hypothesis that G3BP1 has a potential role in regulating PI3K/AKT singling pathway." (PMID 31560169, 2019).
Flavivirus Infections (4 papers, 2022 to 2025). Infections with viruses of the genus FLAVIVIRUS, family FLAVIVIRIDAE. "Lastly, RLR-MAVS-signaling is equivalent between parental, G3BP1/2-KO, or PKR-KO A549 cells in response to poly(I:C) lipofection or flavivirus infection." (PMID 38778761, 2024). "Specifically, knockout of G3BP1/2 in RNase L-null cells, which abolished SG assembly, did not alter RLR-MAVS-IRF3-mediated signaling, induction of interferon β mRNA, or alterations to interferon β protein synthesis in response to dsRNA, 5′-PPP-RNA, or flavivirus infection." (PMID 38778761, 2024). "Combined, our above data argue that neither G3BP proteins nor G3BP1 complexes (SGs or RLBs) alter the activation of the RLR-MAVS-IRF3, OAS/RNase L, or PKR innate immune pathways in response to dsRNA lipofection or flavivirus infection, which contrasts with previous studies." (PMID 38295168, 2024).
nasopharyngeal carcinoma (4 papers, 2024 to 2025). A carcinoma arising from the nasopharyngeal epithelium. "However, G3BP1's involvement in nasopharyngeal carcinoma, delinked from SGs formation, remains an unexplored terrain warranting investigation." (PMID 38164170, 2024). "Ras-GTPase-activating protein (GAP)-binding protein 1 (G3BP1) emerges as a pivotal oncogenic gene across various malignancies, notably including nasopharyngeal carcinoma (NPC)." (PMID 39869565, 2025).
neuroblastoma (4 papers, 2019 to 2025). Neuroblastoma (NB) is the most common solid, extracranial childhood tumor. "To better analyze the kinetics of SG assembly, we induced mild oxidative stress in the SH-SY5Y human neuroblastoma cell line with 50-μM arsenite and then visualized the formation of G3BP1- or PABPC1-positive SGs." (PMID 33362237, 2020). "Therefore, we used CRISPR/Cas9 (clustered regularly interspaced short palindromic repeats/CRISPR-associated protein 9) gene editing technique to insert a GFP tag in frame to the N terminus of the G3BP1 gene in the human neuroblastoma cell line SH-SY5Y." (PMID 30833545, 2019). "In this study, we conducted a genome-wide investigation of the G3BP1- and G3BP2-bound RNAs using enhanced cross-linking and immunoprecipitation-sequencing (eCLIP-seq) in the human neuroblastoma (NB) cell line SH-SY5Y." (PMID 37219408, 2023). "Firstly, we could not obtain the fresh neuroblastoma tissues in which to investigate the nuclear periphery location of G3BP1 and its interaction with TSPYL5." (PMID 40319028, 2025).
arteriosclerosis (3 papers, 2020 to 2022). A vascular disorder characterized by thickening and hardening of the walls of the arteries. "Accordingly, a G3BP antagonist downregulated RIG-I-stimulated G3BP1 methylation; hence, RIG-I and MAVS deficiency reduced osteogenic signals in VSMCs, attenuating arteriosclerosis." (PMID 35693778, 2022). "G3BP1 is a multifunctional protein that participates in many physiological processes, such as SG assembly, immune response, arteriosclerosis, and tumor promotion." (PMID 31996428, 2020).
glioblastoma (3 papers, 2021 to 2025). The most malignant astrocytic tumor (WHO grade IV). "Studies have shown that G3BP1 knockdown inhibits glioblastoma-induced angiogenesis in vivo and promotes bortezomib-induced apoptosis by reducing stress granule formation in glioblastoma multiforme." (PMID 36330442, 2022). "G3BP1 knock-down inhibits cell formation and increases clearance of SGs, thereby sensitizing bortezomib-resistant u78 glioblastoma cells and increasing apoptosis." (PMID 35004322, 2021).